CFTR (CF transmembrane conductance regulator)
Diseases named in the same sentence as CFTR in open-access papers (continued):
Sharing a sentence is not in itself a finding about the gene and the disease.
cystic fibrosis (continued). "Cystic Fibrosis is the most common life-shortening autosomal recessive disorder caused by variants of the cystic fibrosis transmembrane conductance regulator (CFTR) gene." (PMID 40943780, 2025). "Cystic fibrosis is an autosomal recessive condition caused by various mutations in the transmembrane conductance regulator (CFTR) protein and impacts multiple organs, including the pancreas." (PMID 40856269, 2025). "Cystic fibrosis is a genetic disease affecting mainly the respiratory and digestive systems through CFTR gene mutations." (PMID 40933696, 2025). "Variants in the CFTR gene induce aberrant function or the complete lack of the CFTR protein, which causes cystic fibrosis." (PMID 41044511, 2025). "Cystic fibrosis is a life-shortening autosomal recessive disease caused by pathological variants (mutations) in the cystic fibrosis transmembrane conductance regulator (CFTR) gene." (PMID 40700044, 2025). "In cystic fibrosis cells, the loss of functional CFTR impairs the normal endocytic and lysosomal trafficking of TLR4, which remains in early endosomes, failing to be degraded." (PMID 41226119, 2025). "People with cystic fibrosis (pwCF) who carry at least one copy of the F508del mutation in the cystic fibrosis transmembrane conductance regulator (CFTR) gene, or another mutation documented as responsive to ETI, receive ETI therapy." (PMID 41158800, 2025). "Cystic fibrosis is a rare genetic disease with autosomal recessive inheritance, caused by variants in the CF transmembrane conductance regulator (CFTR) gene, that affects approximately 100,000 people worldwide." (PMID 40531731, 2025). "Cystic fibrosis is an autosomal recessive disorder caused by pathogenic mutations in the CF transmembrane conductance regulator (CFTR) gene, encoding a chloride channel responsible for anion transport across epithelial cells." (PMID 40429486, 2025). "Cystic fibrosis is an autosomal recessive disorder caused by mutations in the Cystic Fibrosis Transmembrane Conductance Regulator (CFTR) protein, leading to multisystem manifestations and respiratory failure." (PMID 41373238, 2025). "Ivacaftor is a novel drug designed to treat cystic fibrosis, targeting only those who carry disease-causative CFTR mutations." (PMID 40376268, 2025). "In the CFTR gene, for example, nearly 1700 different mutations lead to varying manifestations of cystic fibrosis with differing prognoses and comorbidities." (PMID 39825393, 2025). "This putative function would be particularly relevant for cystic fibrosis, in which lumen acidification driven by the loss of CFTR-mediated bicarbonate secretion drives gastrointestinal pathophysiology and results in significant co-morbidities." (PMID 40371707, 2025). "Cystic fibrosis is a rare genetic disorder caused by defects in the CFTR protein due to mutations in the CFTR gene." (PMID 40430547, 2025). "A pivotal application is in cystic fibrosis, a genetic disease caused by mutations in the CFTR chloride channel." (PMID 41438702, 2025). "One of the most notable CRISPR applications in stem cell research was the correction of CFTR mutations in cultured intestinal stem cells from cystic fibrosis patients." (PMID 40438407, 2025). "Cystic fibrosis is a recessive genetic disease caused by mutations in the cystic fibrosis transmembrane conductance regulator (CFTR) protein, a chloride and bicarbonate channel localized on the plasma membrane of epithelial cells." (PMID 39996840, 2025). "Cystic fibrosis is caused by a mutation in the CFTR gene, which codes for a protein that functions as a chlorine channel called CFTR (Cystic Fibrosis Transmembrane Conductance Regulator)." (PMID 38541936, 2024). "Cystic fibrosis is a multisystem disorder caused by mutations in the cystic fibrosis transmembrane conductance regulator (CFTR) gene." (PMID 39458161, 2024).
cystic fibrosis (continued). "Homozygosity for F508del CFTR causes the disease cystic fibrosis, which is fatal in childhood if untreated, and (in the absence of in vitro fertilization technology) precludes reproduction among males." (PMID 39024311, 2024). "Cystic fibrosis is a recessive genetic disorder in which the CF transmembrane conductance regulator (CFTR) gene possesses a mutation that disrupts protein function." (PMID 39681187, 2024). "Cystic fibrosis results from mutations in the cystic fibrosis transmembrane conductance regulator (CFTR) anion channel, ultimately leading to diminished transepithelial anion secretion and mucociliary clearance." (PMID 38954478, 2024). "We derived LOs from one hiBC line from a healthy donor (line No5, wild type) and two hiBC lines from donors with cystic fibrosis with a homozygous mutation in CFTR (F508del) (lines No1 and No2, F508del)." (PMID 38737127, 2024). "Cystic fibrosis is caused by mutations in the CF transmembrane conductance regulator (CFTR) gene, with F508del being the most prevalent mutation." (PMID 38646935, 2024). "Cystic fibrosis is a monogenic disease due to the mutation of the cystic fibrosis transmembrane conductance regulator (CFTR) gene, affecting the lungs as well as extrapulmonary tissues including the gastrointestinal tract." (PMID 39200847, 2024). "The specific CFTR pathogenetic variant in the celomic fetal DNA was identified in the homozygous state and the fetus was diagnosticated as being affected by cystic fibrosis (C)." (PMID 38927598, 2024). "For example, cystic fibrosis, caused by pathogenic variants in the CFTR gene, is the most common life-limiting AR disease affecting Caucasians, but is much lower in Asian Americans." (PMID 38297315, 2024). "Pathogenic mutations in CFTR cause cystic fibrosis, a monogenic disease manifesting as chronic airway inflammation." (PMID 38528022, 2024). "CFTR loss-of-function mutations cause cystic fibrosis, and CFTR hyperactivation due to abnormally high PKA activities underlies diarrhea in cholera and cyst growth in autosomal dominant polycystic kidney disease (ADPKD)." (PMID 39495916, 2024). "Cystic fibrosis is a lethal, autosomal recessive disorder that arises from loss-of-function variants in the CF transmembrane conductance regulator (CFTR)." (PMID 38765466, 2024). "The androgen receptor (AR) gene, whose mutations cause androgen insensitivity syndrome and spermatogenic damage, and the CFTR gene, whose mutations cause cystic fibrosis and loss of vas deferens, both play important roles in gonadal differentiation." (PMID 39055413, 2024). "Cystic fibrosis is a genetic disorder caused by cystic fibrosis transmembrane conductance regulator (CFTR) gene mutations." (PMID 38257346, 2024). "Cystic fibrosis is a highly prevalent genetic disorder caused by biallelic pathogenic variants in the CFTR gene, causing an altered function of the exocrine glands and a subsequent spectrum of hypofunctional and degenerative manifestations." (PMID 39062716, 2024). "Cystic fibrosis is a genetic disorder that arises from pathogenic variants in the CF transmembrane conductance regulator (CFTR) gene." (PMID 39183346, 2024). "This novel pharmacological approach is based on the repositioning strategy of “CFTR correctors” developed to treat type II mutations of cystic fibrosis transmembrane-conductance regulator (CFTR) (e.g., F508del) causing cystic fibrosis." (PMID 39273176, 2024). "Loss-of-function mutations in CFTR cause cystic fibrosis, a complex, multi-organ disease, with potentially fatal outcome." (PMID 38262945, 2024). "Cystic fibrosis is caused by mutations within the CF transmembrane conductance regulator (CFTR) gene leading to defective epithelial chloride transport in many organs." (PMID 38610815, 2024). "The most common mutation in CFTR gene in cystic fibrosis is the variant rs113993960 (ΔF508) of CFTR gene (OMIM 602421)." (PMID 39881831, 2024).
cystic fibrosis (continued). "Models trained on data from cells treated with the readthrough-promoting drug, G418, accurately predicted readthrough of premature termination codons arising from CFTR nonsense alleles that cause cystic fibrosis." (PMID 38509072, 2024). "Cystic fibrosis is one of the most common inherited conditions, which causes abnormalities in the cystic fibrosis transmembrane conductance regulator (CFTR) gene." (PMID 38375430, 2024). "Cystic fibrosis is an autosomal recessive disease associated with the mutation in CF transmembrane conductance regulator (CFTR) gene, that encodes a protein of c-AMP gated chloride channel." (PMID 39011515, 2024). "VX-770 is a small-molecule CFTR potentiator that is highly efficacious in individuals with cystic fibrosis caused by mutations in CFTR that result in a defect in channel gating." (PMID 39595555, 2024). "If pathogenic variants are identified, standard procedures apply such as genetic counselling and, especially in case of CFTR-related azoospermia, analysis of the female partner to assess the risk for cystic fibrosis in offspring." (PMID 39253719, 2024). "Cystic fibrosis is an autosomal recessive disorder caused by mutations in the gene encoding for the cystic fibrosis transmembrane conductance regulator (CFTR) protein." (PMID 39196336, 2024). "Variants in the cystic fibrosis transmembrane conductance regulator gene (CFTR) result in cystic fibrosis–a lethal autosomal recessive disorder." (PMID 38271453, 2024). "Enhanced signaling by NFκB and ENaC also marks the airway of patients suffering from cystic fibrosis, a life-limiting proinflammatory genetic disease due to inactivating mutations in the CFTR gene." (PMID 39043712, 2024). "The complete absence of the CFTR protein due to nonsense mutations leads to the most severe form of cystic fibrosis." (PMID 39765719, 2024). "Motivated by this encouraging data, the lung SORT LNPs were further assessed for their therapeutic potential for treatment of cystic fibrosis, a genetic lung disease caused by a C-to-T mutation in the cystic fibrosis transmembrane conductance regulator (CFTR)." (PMID 39397026, 2024). "For CFTR (which is associated with cystic fibrosis), MAGPIE predicted 164 (95%) variants to be pathogenic." (PMID 38185709, 2024). "Cystic fibrosis is caused by mutations in the CF transmembrane conductance regulator (CFTR) gene, which encodes an anion channel that conducts chloride and bicarbonate across epithelia found in multiple organs." (PMID 38646935, 2024). "For instance, the combination of ivacaftor, tezacaftor, and elexacaftorin strongly increases currents and plasma membrane expression of the most frequent mutation of CFTR, causing cystic fibrosis due to abnormal processing of the mutant protein (ΔF508)." (PMID 39336766, 2024). "Cystic fibrosis is caused by mutations in the cystic fibrosis transmembrane conductance regulator (CFTR) gene, which has critical functions in epithelial ion transport and hydration of mucus." (PMID 39133871, 2024). "People with cystic fibrosis, who have a mutation in the CFTR, were less susceptible to SARS-CoV-2 infection." (PMID 39205282, 2024). "Cystic Fibrosis is caused by mutations in the gene that encodes the CF Transmembrane Conductance Regulator (CFTR) protein, which functions as a chloride and bicarbonate channel at the apical membrane of epithelial cells." (PMID 38505263, 2024). "These transporters are linked to diseases like cystic fibrosis (ABCC7/CFTR), Tangier disease, cardiovascular disease (ABCA1), retinitis pigmentosa (ABCA4), and more." (PMID 39238930, 2024). "This is important for the future application of this cell model in the screening of therapeutic compounds aimed at correcting the CFTR mutation and for the development of etiotropic therapy for cystic fibrosis." (PMID 38737127, 2024). "Mutations in the CFTR gene cause cystic fibrosis, a severe genetic disorder characterized by impaired mucociliary clearance and progressive respiratory failure." (PMID 39770445, 2024).
cystic fibrosis (continued). "Dysfunction of the cystic fibrosis transmembrane conductance regulator (CFTR) anion channel by genetic mutations causes the inherited disease cystic fibrosis." (PMID 38699141, 2024). "Pulmonary ionocytes have been identified in the airway epithelium as a small population of ion transporting cells expressing high levels of CFTR (cystic fibrosis transmembrane conductance regulator), the gene mutated in cystic fibrosis." (PMID 38664797, 2024). "Cystic fibrosis is a rare genetic autosomal recessive disorder caused by mutations in the cystic fibrosis transmembrane conductance regulator (CFTR) gene." (PMID 38977662, 2024). "Cystic fibrosis is a genetic disorder caused by mutations in the gene encoding the cystic fibrosis transmembrane conductance regulator (CFTR) epithelial chloride channel." (PMID 38347907, 2024). "Cystic fibrosis is an autosomal recessive chronic disease caused by mutations in the CF transmembrane conductance regulator (CFTR) gene." (PMID 38265526, 2024). "Cystic fibrosis is an autosomal recessive disorder characterized by mutations in the cystic fibrosis transmembrane conductance regulator (CFTR) gene, leading to impaired chloride and sodium transport across epithelial cells." (PMID 39683464, 2024). "Protein kinase A (PKA) regulates many proteins, one of which is cystic fibrosis transmembrane conductance regulator (CFTR), the ion channel underlying the lethal disease cystic fibrosis." (PMID 39495916, 2024). "Such organoid phenotypes have been highly instrumental for the studying of diseases, including cystic fibrosis, which is characterized by genetic mutations of the CF transmembrane conductance regulator (CFTR) ion channel." (PMID 38480810, 2024). "Cystic fibrosis is the most common autosomal recessive multisystem disease worldwide due to the ΔF508 mutation in gene 7 encoding the CFTR (CF transmembrane conductance regulator) chloride ion channel." (PMID 38339178, 2024). "Cystic fibrosis is an autosomal recessive genetic disease that is caused by mutations in the gene responsible for the CF transmembrane conductance regulator (CFTR)." (PMID 38463712, 2024). "Cystic fibrosis is caused by CFTR dysfunction which leads to imbalanced ion homeostasis and recurrent bacterial infections in the airways, accompanied by chronic neutrophilic inflammation." (PMID 39732786, 2024). "Cystic fibrosis is a relatively common autosomal recessive disorder caused by mutations in the CFTR gene." (PMID 39765719, 2024). "Cystic Fibrosis causing mutations in the gene CFTR, reduce the activity of the CFTR channel protein, and leads to mucus aggregation, airway obstruction and poor lung function." (PMID 38982492, 2024). "Cystic fibrosis is the most prevalent autosomal recessive genetic condition caused by mutations in the cystic fibrosis transmembrane conductance regulator (CFTR) protein, which regulates chloride and bicarbonate transport in epithelial cells." (PMID 38541202, 2024). "Cystic fibrosis is a genetic disorder caused by mutations in the cystic fibrosis transmembrane conductance regulator (CFTR) gene, resulting in defective chloride ion channels." (PMID 39408877, 2024). "Cystic fibrosis development is related to CFTR gene mutations, which result in chloride canal function impairment controlling water and ion secretion and absorption in epithelial tissues." (PMID 39881831, 2024). "Cystic fibrosis is a genetic autosomal recessive disorder that causes a mutation in CF transmembrane conductance regulator (CFTR) protein, resulting in abnormalities in epithelial ionic transport." (PMID 39194031, 2024). "The cystic fibrosis transmembrane conductance regulator (CFTR), the loss of which causes cystic fibrosis, is expressed throughout the gastrointestinal tract, and in the absorptive epithelial cells of the small intestine." (PMID 39002195, 2024).
cystic fibrosis (continued). "Loss of function of the CFTR chloride channel on the surface of airway epithelial cells is known to cause mucus obstruction in the genetic disease, Cystic Fibrosis." (PMID 38982492, 2024). "In the high-altitude, low-oxygen environments where yaks reside, maintaining the functional integrity of the CFTR protein is crucial to prevent the development of cystic fibrosis in the lungs, a risk heightened by hypoxia." (PMID 38779034, 2024). "Cystic fibrosis is a life-threatening disease that is caused by mutations in CFTR, a gene which encodes an ion channel that supports proper function of several epithelial tissues, most critically the lung." (PMID 39439894, 2024). "Cystic fibrosis is a genetic ailment caused by mutations in the cystic fibrosis transmembrane conductance regulator (CFTR) gene." (PMID 38694803, 2024). "A cystic fibrosis ferret model harboring the CFTR-F508del mutation was created to evaluate in utero and postnatal therapeutic efficacy of CFTR modulators." (PMID 38646935, 2024). "We differentiated five hiPSC lines into hiBCs: two lines from healthy donors (No4 and No5) and three lines from cystic fibrosis patients with homozygous (No1 and No2) or heterozygous (No3) F508del mutations of the CFTR gene." (PMID 38737127, 2024). "Cystic fibrosis is an inherited disease, which is caused by the CFTR protein defects due to mutations in the CFTR gene." (PMID 38229125, 2024). "Mutations in the gene encoding the cystic fibrosis transmembrane conductance regulator (CFTR) are the molecular cause of the progressive autosomal recessive disorder Cystic Fibrosis, which affects more than 100,000 individuals worldwide." (PMID 38398574, 2024). "Cystic fibrosis is one of the most prevalent autosomal recessive diseases and is created by a mutation in the transmembrane conductance regulator (CFTR)." (PMID 39199292, 2024). "Cystic fibrosis is caused by mutations in the CFTR gene (CF transmembrane conductance regulator) that result in defective cellular chloride transport." (PMID 38442240, 2024). "Encoded by the CFTR gene, a protein that controls the body’s transportation of water and chloride breaks down in cystic fibrosis." (PMID 39065790, 2024). "Missense variants that alter a single amino acid in the CFTR protein are among the most common cystic fibrosis variants, yet tools for accurately predicting molecular consequences of missense variants have been limited to date." (PMID 38271453, 2024). "This work highlights the potential of silibinins and curcumin natural derivatives as therapeutic medicines for cystic fibrosis associated with mutant CFTR proteins by thorough molecular docking, molecular dynamics simulations, and ADME studies." (PMID 39043981, 2024). "Cystic Fibrosis is an inherited genetic disorder caused by mutations in the CFTR gene, which encodes a chloride ion channel." (PMID 39026347, 2024). "Cystic fibrosis is an autosomal-recessive disorder caused by mutations in a gene located on the long arm of chromosome 7 that encodes the CF transmembrane conductance regulator (CFTR) protein, which is expressed in many epithelial cells." (PMID 39624565, 2024). "Cystic fibrosis is an autosomal recessive, life-shortening disease caused by mutations in the cystic fibrosis transmembrane conductance regulator (CFTR) gene." (PMID 38916781, 2024). "This pharmacological treatment is based on the employment of molecules named CFTR correctors, developed to treat type II mutations of CFTR) (e.g., F508del) causing Cystic Fibrosis." (PMID 39273176, 2024). "Cystic fibrosis is a progressive, genetic disease caused by CF transmembrane conductance regulator (CFTR) protein dysfunction, leading to cyclical lung infection and inflammation." (PMID 38678203, 2024). "Cystic fibrosis is a hereditary condition caused by mutations in the gene encoding the cystic fibrosis transmembrane conductance regulator (CFTR) protein." (PMID 38169295, 2024).